CCDC110 (coiled-coil domain containing 110)
Synonyms: CT52; KMHN1; KM-HN-1; MGC33607
Tractability: No criterion of Open Targets' tractability assessment is met for any kind of drug.
Gene: Protein-coding gene on chromosome 4 (185,445,182 to 185,471,752, reverse strand). Ensembl gene ENSG00000168491.
Subcellular location: Nucleus
Subcellular location (Human Protein Atlas): Nucleoplasm; Cytosol
Gene Ontology:
Molecular function: protein binding
Cellular component: nucleoplasm; cytoskeleton; nucleus
Genetic constraint (gnomAD): Loss-of-function variants: 59 observed, 63.45 expected, observed/expected ratio (o/e) 0.93, 90% interval 0.75 to 1.15. The upper end of that interval is the gene's LOEUF score, 1.15, which puts it in group 5 of 6, group 1 being the genes least tolerant of losing a copy. Missense variants: 801 observed, 895.64 expected, observed/expected ratio (o/e) 0.89, 90% interval 0.84 to 0.95. Synonymous variants: 273 observed, 301.82 expected, observed/expected ratio (o/e) 0.9, 90% interval 0.82 to 1.
Homologues: Orthologues: macaque CCDC110 (93% identical), guinea pig CCDC110 (75% identical).
Diseases named in the same sentence as CCDC110 in open-access papers:
CCDC110 is named in the same sentence as 9 diseases in open-access papers, as found by Europe PMC text mining. Sharing a sentence is not in itself a finding about the gene and the disease. The quoted sentences say what the papers report.
breast carcinoma (1 paper, 2024). "Coiled-Coil Domain Containing 110 (CCDC110) is expressed in numerous cancers including esophageal cancer, breast cancer, colon cancer, melanoma, hepatocellular carcinoma, gastric cancer, and pancreatic cancer." (PMID 38596293, 2024).
CCDC110 also shares sentences with these, for which no sentence is quoted: cancer (2 papers); colon cancer (1); esophageal cancer (1); gastric cancer (1); hepatocellular carcinoma (1); melanoma (1); pancreatic cancer (1); testis cancer (1).